CD4 (CD4 molecule)
Diseases named in the same sentence as CD4 in open-access papers (continued):
Sharing a sentence is not in itself a finding about the gene and the disease.
infection (continued). "It is now well accepted that protective immunity induced by attenuated Plasmodia sporozoites is multi-factorial involving antibodies, CD4+ T cells as well as other lymphocytes, but that the CD8+ T cells are the main effectors against pre-erythrocytic infection." (PMID 19347042, 2009). "This humanized model was improved upon, and it was shown that CD4+T cells in the peripheral blood, spleen, and bone marrow expressed both CXCR4 and CCR5 antigens and showed a long-lasting viremia after infection with HIV-1 viral isolates specific for both receptors." (PMID 19674458, 2009). "Also, broadly speaking there were increases in the proportion of B cells (following an initial decrease at 14 dpi) and reductions in the proportions of various T cell subpopulations (CD4+, CD8+ and δγ T cells) over the course of infection." (PMID 19409086, 2009). "The 155T3 envelope, which differs from the 239 envelope by 22 amino acids in gp120, uses CXCR4 rather than CCR5 as a co-receptor for infection of both naive and memory CD4+ T lymphocytes." (PMID 19165322, 2009). "Nonproliferating quiescent CD4+ T-cells are resistant to the infection with human immunodeficiency virus type 1 (HIV-1) unless they are activated by mitogenic stimulation or by cytokine stimulation." (PMID 19300495, 2009). "Firstly, CD4 T cells must be activated before they can be productively infected, a process that includes cell division, while productive infection can be established in macrophages even though they are not dividing." (PMID 19492063, 2009). "To determine whether CD4 or CD8 T cells played a role in PCN-mediated protection against influenza virus we depleted T cell subsets prior to and after infection." (PMID 19774076, 2009). "Consistent with previous reports, SIVmac251 infection induced a decrease in blood CD4+ and CD8+ T-cell and NK-cell counts, detectable by D7 p.i., but reaching their nadir on D14 p.i., with reductions of 53% for CD4+, 49% for CD8+ and 85% for NK cells." (PMID 19543531, 2009). "This demonstrated that the CD4 T cells in both the Ag85B and TB10.4 pool of T cells were initially recruited/expanded more than the CD8 T cells, even though both cell types were clearly recruited to the lung at the onset of the infection." (PMID 19357780, 2009). "The strongest CD4+ T cell response to HCV infection has been shown to occur within the first six months after infection regardless of outcome." (PMID 21994550, 2009). "To analyze whether there was a more extensive recruitment, or expansion, of CD4 versus CD8 T cells, we next quantified the cell proportions of Ag85B and TB10.4 specific CD4 or CD8 T cells before and after infection." (PMID 19357780, 2009). "However, the cytotoxicity of CCR5 tropic Env proteins is relatively reduced, explaining why CD4+ T lymphocyte depletion is generally mild and can only be slightly enhanced by Nef in HLAC infections with R5-tropic strains." (PMID 19146681, 2009). "For both sCD4 and 191, the enhancement of infection of cells lacking CD4 became progressively less efficient at higher concentrations; in some cases, decreases in viral infectivity were associated with escalating doses." (PMID 19343205, 2009). "Thus, we measured the levels of peripheral blood B cells as well as CD4 and CD8 T cells at different time points after a sublethal IAV-infection." (PMID 19290047, 2009). "The frequency of circulating CD4+CD25+ cells (the cell population in which Treg are predominantly contained) in the blood of HCV carriers was higher than in healthy donors and individuals who had resolved the infection." (PMID 20041222, 2009). "In comparison to non-infected Se-adequate (Group I) mice, Group II mice in the absence of any infection exhibited significantly reduced percentages of CD4+ and CD8+ T cells (p < 0.01)." (PMID 19852827, 2009). "In vitro, dendritic cells (DCs) bind and transfer intact, infectious HIV to CD4 T cells without first becoming infected, a process known as trans-infection." (PMID 18725936, 2008).
infection (continued). "However, we cannot rule out that CXCR4+ cells in the prostate are mainly inactivated/naive CD4+T cells and/or CD8+T lymphocytes, both refractory to productive infection." (PMID 19117522, 2008). "Overall, there was no significant change in geometric mean log viral loads or CD4+ counts between either 6–12 and 12–18 months post-infection, or 12–18 and 18–24 months post infection (p>0.2; Wilcoxon matched pairs test)." (PMID 18369479, 2008). "Enhanced macrophage-tropism of HIV in brain tissue may result from an adaptation for infection of macrophage-lineage cells, while HIV-1 replicating in immune tissue may have adapted for replication in CD4+ T-cells." (PMID 18205925, 2008). "However, this immune regulation can counteract the function of CD4+ or CD8+ effector T cells and paradoxically dampen the control of infection." (PMID 18665224, 2008). "In this work, it was observed that DCs isolated from infected mice at different times after infection are not able to establish strong interactions and prime naïve CD4+ T cells." (PMID 18495039, 2008). "NP-2/CD4/FPRL1 cells were resistant to infection by IIIB, Ba-L, GUN-1V, GUN-4WT, GUN-7V, and SF162 strains: less than 0.1% cells were HIV-1 antigen-positive on day 6 after infection." (PMID 18577234, 2008). "However, by day 10 the total number of infiltrating cells and the number of CD4+ and CD8+ T cells were reduced after infection with vΔC16, consistent with more rapid resolution of the infection." (PMID 18796705, 2008). "The results observed with FIV-infected lion and puma parallels human (HIV) and Asian monkey (SIV) CD4+ diminution, and suggests there may be an immunological cost of FIV infection in these two species of large cats." (PMID 18251995, 2008). "NP-2/CD4/GPR1 and NP-2/CD4 cells were resistant to infection by all of these primary isolates." (PMID 18577234, 2008). "The impairment in the CD4+ T cell responses was observed only during the memory phase of the infection and not the primary phase." (PMID 18389078, 2008). "Here we use a model primary CD4+ T cell response in vitro to show that individual CD4+ T cells that secrete anti-viral CCR5 ligands are ‘self-protected’ against infection with R5 but not X4 strains of HIV-1." (PMID 18941536, 2008). "Interestingly the frequencies and numbers of IL-10+ CD4+TCR-β+ cells were equivalent in PyL and PyNL infected mice on day 7 post-infection." (PMID 18401464, 2008). "However, by day 10 there was a reduction in CD4+ and CD8+ T cells present after infection with vΔC16." (PMID 18796705, 2008). "From our results, we observed that CD8+ T-cells were able to support productive infection with T-cell tropic viral strains independent of CD4 cell-surface expression." (PMID 18923697, 2008). "In this study, a partially inhibitory effect of the fMLF peptide on the FPRL1-mediated infection with HIV/SIV strains was observed, while anti-CD4 MoAb NuTH/I could almost completely block it." (PMID 18577234, 2008). "Lack of any of the three components of the adaptive response: B cells, CD4 T cells, or CD8 T cells significantly diminished vaccine effects generated by either live virus or VP1 capsid protein immunization, and delayed viral clearance during primary infection." (PMID 19079577, 2008). "Unlike infection in activated primary CD4+ T cells or cell lines, HIV-1 infection of macrophages is not generally lytic." (PMID 18241354, 2008). "An additional case of a LTNP is an Italian homosexual whose CD4+ T cell levels have not altered in 20 years of infection and whose viral loads have been steady at the extremely low value of about 200 copies/ml." (PMID 18808677, 2008). "In this report, we extend those studies by showing that individual CD4+ T cells which synthesize anti-viral CCR5 ligands are ‘self-protected’ against infection with R5 but not X4 isolates of HIV-1 during the primary immune response in vitro." (PMID 18941536, 2008).
infection (continued). "Notably, in a more recent study, in addition to CD4 and CXCR4, CCR5 was detected on the surface of megakaryocytes, and infection of these cells with both CCR5-tropic and CXCR4-tropic HIV-1 has been reported." (PMID 19112504, 2008). "Thus R5 envelopes from brain tissue were highly macrophage-tropic and were able to exploit low amounts of CD4 and/or CCR5 for infection." (PMID 18205925, 2008). "Each round of infection and sorting resulted in an approximate 3-fold enrichment of CD4-negative cells relative to the preceding round, with a total enrichment of 47-fold." (PMID 19008949, 2008). "In the absence of HIV treatment, ongoing viral replication and infection of cells leads to CD4+ cell destruction and depletion resulting in immune system dysfunction." (PMID 19936197, 2008). "A possible explanation for this observation may be due to the low expression of the CD4 molecule on the surface of CD8+ T-cells and subsequent down-regulation of this receptor following infection." (PMID 18923697, 2008). "Notably, more CD4+ cells were observed in granulomas of both wild-type and OBF-1-null mice at eight weeks post-infection than at five weeks post-infection." (PMID 18320044, 2008). "Notably, all probed CD4-specific DARPins from the 1st and the 2nd, affinity improved series inhibited HIV entry both in cell line and primary cell based infection systems." (PMID 18654624, 2008). "To determine mechanism of the observed inhibition of infection, we tested for SP4-2 activity against HIV-1 fusion to CD4-expressing SupT1 T cells, by utilized a highly specific and sensitive fluorescence resonance energy transfer (FRET)-based HIV-1 fusion assay." (PMID 18197976, 2008). "20% (27 cases) retained their CD4+ T-cell counts >600 in HIV/HCV group even at month 33 visit whereas none does so in HIV mono-infection group since month 21 visit." (PMID 19098990, 2008). "Direct evidence of trans-infection mediated by mannose receptors in DCs is lacking, but in macrophages, these receptors appear to play an important role in the trans-infection of CD4 T cells." (PMID 18584030, 2008). "The decrease of CD4+CD25+ cells before infection did not result in the increased production of IL-4 and other cytokines in C57BL/6 mice." (PMID 18414636, 2008). "After infection, cultures were washed and co-cultured with autologous CD4 T cells, without C14, and half of the culture supernatant was refreshed twice weekly with culture medium without compound." (PMID 18522743, 2008). "When we analyzed the percentage of CD4+ or CD8+ cells expressing CD44hiCD62Llo 30 or 70 days post-infection, we verified that only BCGin/DNA group presented significant expression of CD44hiCD62Llomolecules on CD4+ cells in relation to BCGsc, DNA-HSP65 and infected mice 70 days post-infection." (PMID 17714584, 2007). "The proportion of CD4+CD8+ DP cells was not different at 5 days post-infection (73.2%), but dropped to 26% at 10 days post-infection." (PMID 17326843, 2007). "Although selective removal of LC from epithelial tissue sheets was not possible, we concluded that infection of intraepithelial CD4+ T cells did not require LC based on several lines of evidence reported here." (PMID 17306567, 2007). "However, the numbers of transferred CD4+CD25+ regulatory T cells are small and work better in a local and specific manner since these cells suppress the immune response to tumors and infections." (PMID 17284325, 2007). "Similar lysis experiments were not performed with NP-2/CD4/CCR5 cell lines because these infections showed stronger cytopathic effect (large syncytia and pronounced cell death) than NP-2/CCR5 cultures." (PMID 17645788, 2007). "One scenario has been reproduced by our experiments: the low or non-productive infection of CD4 negative cells was amplified by contact with PBMC." (PMID 17645788, 2007).
infection (continued). "We also used HIV-1 pseudotyped with the envelope glycoprotein G of vesicular stomatitis virus (VSV-G) to efficiently infect CD4-negative HFA to compare productive infection to virus binding for induction of cellular genes." (PMID 17498309, 2007). "The degree of the decrease of CD4+CD8+ DP cells in the non-lethal infection was not as dramatic as in the lethal infection." (PMID 17326843, 2007). "No syncytia induction or viral antigen production was observed in the U87.CD4 parental cells in parallel infections with the SIVsm isolates (data not shown)." (PMID 17645788, 2007). "The HIV-1 interaction with astrocytes is likely to be mediated by the viral envelope glycoprotein gp120 because preincubation of GFP-Vpr tagged virions with soluble CD4 prevented HIV-1 binding in our study and it was shown to block astrocyte infection by HIV-1 in a previous report." (PMID 17498309, 2007). "As expected, none of the BCG+ subjects without infection gave ESAT-6-specific CD4 Th1 cell responses." (PMID 17655752, 2007). "Change in phenotype from CD4-independent-LOW to CD4-independent-HIGH was only observed in one animal and in two macaques the CD4-independent-LOW phenotype did not seem to change throughout infection." (PMID 17645788, 2007). "Note that the quiescent phenotype of target CD4+ T cells did not significantly change upon infection, as determined by monitoring the surface expression of T cell activation markers (CD25 and HLA-DR) of infected and control cells by flow cytometry." (PMID 17845727, 2007). "It was determined that A) SHIVSF162P4 down-regulated the CC-chemokine gene expression during acute stage of infection to a greater extent (p<0.05) than SHIVKu1, and B) such down-regulation was not paralleled with the CD4+ T cell depletion." (PMID 17684570, 2007). "Conversely, we have not observed high-frequency responses to CD4+ T cell antigens in those without evidence of infection with Mtb." (PMID 17892322, 2007). "This is reflected in later patency of infection, lower peak parasitaemia, and increases in the number of IFN-γ+ and IL-4+ CD4+ T cells in the blood stage of infection in mice given first non-infectious bites." (PMID 17555592, 2007). "The 3 animal groups had similar viral RNA levels in plasma and infectious titers in PBMC, and a similar decline in absolute counts and percentages of CD4+ T lymphocytes and CD4+/CD8+ T cell ratios during the first 20 weeks of infection (two-way ANOVA: p values of passage effect >0.05)." (PMID 17417971, 2007). "The infection rate constant, k0, the timescale of CD4 down-modulation, td, and the recombination rate, ρ, are not well-established, and we vary these parameters over ranges that define their best current estimates." (PMID 17967052, 2007). "macaque 95020 failed to control active viral replication and depletion of CD4+ T cells throughout the course of primary infection." (PMID 17132170, 2006). "First, neither pre-infection CD4 levels nor the exact timing of the initial infection were known, as patients were deemed to be in acute stage of infection based on viremia in the face of negative serology." (PMID 17147469, 2006). "A higher number of activated CD4 T cells in UCs may allow a more rapid onset of HIV-1 replication, which would then promote a more efficient spread of infection upon PHA-activation." (PMID 16792805, 2006). "Latently HIV-1 infected CD4+ T cells can be obtained in this model, but the exact extent to which it can be applied to natural infection is not known." (PMID 16412247, 2006). "The researchers found that the percentage of CD4 lymphocytes dropped much lower in the intestinal mucosa than in blood during early infection and then, unlike in blood, remained low even after several years of treatment for HIV." (PMID 17147468, 2006). "Previous qualitative PCR analysis of viral replication in CD4 T cells from subject W276 suggested that the restriction step occurred before integration, but early times post-infection were not analyzed." (PMID 17092330, 2006).
infection (continued). "The "post-CD4" format involves pre-incubating virus with sCD4 and graded concentrations of a nAb, then measuring residual infection of CD4 negative Cf2.Th.synCCR5 cells." (PMID 16817962, 2006). "Whilst blockade of cell surface receptors (CD4, CCR5 and CXCR4) within the mucosa may prevent localised infection of T cells and macrophages, viral uptake and dissemination by DC occurs through CD4 and MCLRs." (PMID 16882346, 2006). "This indicates that the origin of the CD4 anchor was not critical for receptor function during infections, which is consistent with earlier observations that Env binding needed for infection maps near the amino terminus (amino acids 40–60) of CD4." (PMID 16371160, 2005). "HIV-specific, CD4-independent superinfection resistance has been described that occurs early after initial infection, but the proteins involved have not been identified conclusively." (PMID 16107223, 2005). "Our previous studies demonstrated that both the X4 and R5 types of HIV can infect CD4(-) cells, and for many types of CD4(-) cells, gp120 is not required for infection." (PMID 16368003, 2005). "This was when HAART was in its infancy and treatment was initiated in a large proportion of HIV positive individuals, regardless of infection stage or CD4 count, because a "hit hard, hit early" consensus existed for patient management." (PMID 16153307, 2005). "They found resting peripheral CD4+ T cells that are not permissive for infection express the enzymatically active version of A3G." (PMID 16293194, 2005). "Long-term follow-up indicated that the transitory presence of such a small number of cells producing such small amounts of MaIFN-β did not prevent animals from the progressive decrease in CD4+ cell count typical of infection with simian immunodeficiency virus." (PMID 15447786, 2004). "Using a Rag KO transfer model, we demonstrate that CD4+ T cells enhance effector differentiation of inflationary CD8+ T cells when present during priming, or when introduced at late timepoints post-infection, indicating a continuous, priming-independent support mechanism." (PMID 42307036, 2026). "The clear phenotypic alteration of the CD4 T cell compartment observed in SBTI suggests that the type II IFN-responsive cells also play an important role during a BTI, potentially in the orchestration of immune responses and protection from recurrent infection." (PMID 41384750, 2026). "Finally, our study did not track the onset or fate of CD4+ T cell responses in infections that persisted." (PMID 40956619, 2025). "In accordance with the prominent CD103+ALDH+ DC population detected in MLN, BALB/c displayed a significant rise of Treg frequencies at day 6 post-infection, whereas CD4+ T cells of C57BL/6 mice comprised similar proportions of Foxp3+ T cells irrespective of the infection status." (PMID 39910093, 2025). "Clustering of antigen-specific CD4+ T cells at the T–B cell border regions in the antigen-draining LN has also been observed in other Th2-biased conditions such as subcutaneous immunization with OVA and papain or alum and infection with a helminth parasite Nippostrongylus brasiliensis." (PMID 41000383, 2025). "Future studies could leverage a similar approach to screen a larger number of epitopes and determine the frequency and durability of CD4+ T cell responses to LISP1 and other candidate liver stage antigens following both natural infection and attenuated sporozoite vaccination strategies." (PMID 39993000, 2025). "This way, in the context of a limited or delayed CD4 T cells engagement, as a consequence of a DENV vaccine design or a mild natural infection with limited specific epitopes presentation, the EF and GC responses may not be mutually exclusive but dynamically regulated." (PMID 41295476, 2025). "Moreover, CD4+ T cells were specifically required for efficient viral clearance from the nasal airways, underscoring their critical role in mediating antiviral immunity during XBB.1.5 infection." (PMID 40822581, 2025).